MIR135A1 (microRNA 135a-1)
Synonyms: hsa-mir-135-1; hsa-mir-135a-1; MIRN135-1; MIRN135A1; mir-135a-1
Gene: MicroRNA gene on chromosome 3 (52,294,219 to 52,294,308, reverse strand). Ensembl gene ENSG00000207926.
Gene Ontology:
Biological process: miRNA-mediated post-transcriptional gene silencing
Cellular component: RISC complex
Homologues: Orthologues: chimpanzee ptr-mir-135a-1 (100% identical), macaque mml-mir-135a-1 (100% identical), pig ssc-mir-135-1 (99% identical), rabbit MIR135A1 (98% identical), guinea pig MIR135A1 (97% identical), dog MIR135A1 (94% identical), mouse Mir135a-1 (92% identical), zebrafish mir135b (63% identical). Paralogues in human: MIR135B (67% identical), MIR135A2 (66% identical).